IGHV1-18 (immunoglobulin heavy variable 1-18)
Description:
V region of the variable domain of immunoglobulin heavy chains that participates in the antigen recognition. Immunoglobulins, also known as antibodies, are membrane-bound or secreted glycoproteins produced by B lymphocytes. In the recognition phase of humoral immunity, the membrane-bound immunoglobulins serve as receptors which, upon binding of a specific antigen, trigger the clonal expansion and differentiation of B lymphocytes into immunoglobulins-secreting plasma cells. Secreted immunoglobulins mediate the effector phase of humoral immunity, which results in the elimination of bound antigens. The antigen binding site is formed by the variable domain of one heavy chain, together with that of its associated light chain. Thus, each immunoglobulin has two antigen binding sites with remarkable affinity for a particular antigen. The variable domains are assembled by a process called V-(D)-J rearrangement and can then be subjected to somatic hypermutations which, after exposure to antigen and selection, allow affinity maturation for a particular antigen.
Synonyms: IGHV118
Gene: Immunoglobulin variable (V) gene on chromosome 14 (106,184,901 to 106,185,394, reverse strand). Ensembl gene ENSG00000211945.
Subcellular location: Secreted; Cell membrane
Gene Ontology:
Molecular function: antigen binding
Biological process: immunoglobulin mediated immune response
Cellular component: extracellular region; plasma membrane
Homologues: Orthologues: mouse Ighv1-50 (68% identical), mouse Ighv1-55 (68% identical), mouse Ighv1-53 (68% identical), mouse Ighv1-74 (68% identical), mouse Ighv1-64 (67% identical), mouse Ighv1-69 (66% identical), mouse Ighv1-85 (66% identical), mouse Ighv1-66 (65% identical), mouse Ighv1-81 (65% identical), mouse Ighv1-59 (64% identical), mouse Ighv1-61 (64% identical), mouse Ighv1-52 (63% identical), and 47 more. Paralogues in human: IGHV1-3 (87% identical), IGHV1-2 (86% identical), IGHV1OR15-1 (82% identical), IGHV1-46 (81% identical), IGHV1-69 (81% identical), IGHV1-69D (81% identical), IGHV1-45 (79% identical), IGHV1-24 (78% identical), IGHV1-58 (78% identical), IGHV7-4-1 (76% identical), IGHV1-69-2 (74% identical), IGHV1OR21-1 (74% identical), and 65 more.
Diseases named in the same sentence as IGHV1-18 in open-access papers:
IGHV1-18 is named in the same sentence as 1 disease in open-access papers, as found by Europe PMC text mining. Sharing a sentence is not in itself a finding about the gene and the disease.
IGHV1-18 shares sentences with these, for which no sentence is quoted: nephropathies (1 paper).